WDFY4 (WDFY family member 4)
Description:
Plays a critical role in the regulation of cDC1-mediated cross-presentation of viral and tumor antigens in dendritic cells. Mechanistically, acts near the plasma membrane and interacts with endosomal membranes to promote endosomal-to-cytosol antigen trafficking. Also plays a role in B-cell survival through regulation of autophagy.
Synonyms: C10orf64; KIAA1607; Em:AC060234.3; FLJ45748
Tractability: PROTAC: ubiquitination databases record sites on it; its protein half-life has been measured.
Gene: Protein-coding gene on chromosome 10 (48,684,873 to 48,982,959, forward strand). Ensembl gene ENSG00000128815.
Subcellular location: Early endosome; Endoplasmic reticulum
Subcellular location (Human Protein Atlas): Nucleoplasm; Cytosol
Gene Ontology:
Biological process: antigen processing and presentation
Cellular component: early endosome; endoplasmic reticulum
Genetic constraint (gnomAD): Loss-of-function variants: 153 observed, 331.23 expected, observed/expected ratio (o/e) 0.46, 90% interval 0.4 to 0.53. The upper end of that interval is the gene's LOEUF score, 0.53, which puts it in group 2 of 6, group 1 being the genes least tolerant of losing a copy. Missense variants: 3,681 observed, 3,945.9 expected, observed/expected ratio (o/e) 0.93, 90% interval 0.91 to 0.96. Synonymous variants: 1,580 observed, 1,591.3 expected, observed/expected ratio (o/e) 0.99, 90% interval 0.95 to 1.03.
Homologues: Orthologues: chimpanzee WDFY4 (99% identical), macaque WDFY4 (96% identical), dog WDFY4 (84% identical), pig WDFY4 (84% identical), rabbit WDFY4 (83% identical), mouse Wdfy4 (81% identical), guinea pig WDFY4 (81% identical), rat Wdfy4 (80% identical), tropical clawed frog wdfy4 (42% identical), Caenorhabditis elegans wdfy-3 (26% identical), Caenorhabditis elegans sel-2 (12% identical), zebrafish wdfy4 (12% identical). Paralogues in human: WDFY3 (36% identical), LYST (20% identical), NBEAL2 (17% identical), NBEAL1 (16% identical), NBEA (15% identical), LRBA (14% identical), NSMAF (8% identical).